VIM (vimentin)
Diseases named in the same sentence as VIM in open-access papers (continued):
Sharing a sentence is not in itself a finding about the gene and the disease.
hepatocellular carcinoma (153 papers, 2009 to 2026). A malignant tumor that arises from hepatocytes. "We also explored the molecular mechanisms associated with the upregulation of vimentin mediated by LASP1 in HBX-positive hepatoma cells." (PMID 33722250, 2021). "Next, we explored the mechanisms associated with the increase of vimentin mediated by LASP1 in HBX-positive hepatoma cells." (PMID 33722250, 2021). "Vimentin has been reported to be acetylated at K120, and deacetylation of this site is associated with increased migration of hepatocellular carcinoma cells." (PMID 34605151, 2021). "In our previous study, we have shown that downregulation of vimentin by Sendai F/HN viroplexes caused vimentin siRNA to inhibit the growth of hepatocellular carcinoma in vitro, which suggests again that vimentin is a potential target for gene therapy." (PMID 28335269, 2016). "In addition, CCL20 has been implicated in the upregulation of vimentin in hepatocellular carcinoma, which supports our findings that vimentin was significantly increased in diabetic AFBs due to calcified plus AGEs diabetic VSMC CM treatment." (PMID 36835011, 2023). "In hepatocellular carcinoma, expression of vimentin was mainly associated with metastasis." (PMID 37717112, 2023). "By specifically targeting and reducing the expression of TGF-β1, FSCN1 (Fascin Actin-Bundling Protein 1), and vimentin, EA exhibited the potential to obstruct pivotal processes closely associated with the development and progression of hepatocellular carcinoma (HCC)." (PMID 38002335, 2023). "Besides, the biological functions and potential molecular mechanisms associated with vimentin mediated by HBX via LASP1 in hepatoma cells was also investigated." (PMID 33722250, 2021). "However, whether these signal pathways are associated with the expressions of vimentin mediated by LASP1 in HBX-positive hepatoma cells is unknown." (PMID 33722250, 2021). "MiR-223-3p inhibits EMT occurrence in hepatocellular carcinoma cells by affecting E-cadherin and Vimentin expression through downregulation of the expression of target gene, FAT1." (PMID 40109856, 2025). "APS have been shown to inhibit the EMT in hepatocellular carcinoma cells by upregulating epithelial markers such as E-cadherin and concurrently downregulating mesenchymal markers, including N-cadherin and vimentin." (PMID 40649307, 2025). "In hepatocellular carcinoma down-regulation of Cx32 led to an increase in vimentin and Snail and a down-regulation of E-cadherin." (PMID 36829482, 2023). "Overexpression of TRAF4 can modify the phosphorylation of Akt as well as the expression of Slug, E-cadherin, and vimentin in hepatocellular carcinoma cells." (PMID 36625999, 2023). "Compared with control treatment, treatment with CCL8 triggered the migration of HepG2 hepatoma cells, substantially increased their levels of vimentin and SNAI1 expression, and downregulated their levels of E-cadherin expression." (PMID 35362480, 2022). "In summary, the present study characterized the expression and associated molecular functions of vimentin mediated by HBX in HCC and identified LASP1 as a regular of vimentin protein expression in HBX-positive hepatoma cells." (PMID 33722250, 2021). "Transwell and wound healing assays were next utilized to investigate the effect of vimentin in cell migration mediated by LASP1 in HBX-positive hepatoma cells." (PMID 33722250, 2021). "Our results demonstrated that LASP1 was a pivotal modulator of the molecular characteristics of EMT by regulating vimentin in HBX-positive hepatoma cells." (PMID 33722250, 2021). "The stability of vimentin was determined after the hepatoma cells were treated with a protein synthesis inhibitor CHX." (PMID 33722250, 2021).
hepatocellular carcinoma (continued). "MALAT1 is capable of inducing VIM gene expression in hepatocellular carcinoma leading to the increase in migration and invasion of these cells." (PMID 35178360, 2021). "We found that the expression of E-cadherin was declined, but β-catenin was enhanced in vimentin-overexpressed hepatoma cells." (PMID 33722250, 2021). "EMT mediated by overexpression of TWIST is associated with hepatocellular carcinoma (HCC) cell invasion and metastasis, possibly through the mediation of Cullin 2 (Cul2) circular RNA to increase the expression of vimentin." (PMID 34298613, 2021). "We also measured the expression of vimentin, E-cadherin, and β-catenin proteins in hepatoma cells by immunofluorescence assay." (PMID 33722250, 2021). "When HBX-positive cells with decreased LASP1 were treated with vimentin expression vectors, the migration capability of hepatoma cells was enhanced." (PMID 33722250, 2021). "IGFPB2 was revealed as a downstream target of overexpressed HSP27 in hepatocellular carcinoma cells, driving tumor proliferation, migration, and invasiveness by inducing vimentin, snail, and β-catenin." (PMID 34830078, 2021). "After HBX-positive hepatoma cells were treated with vimentin shRNA, the cellular proliferation mediated by HBX was reduced." (PMID 33722250, 2021). "When HBX-positive cells were treated with vimentin shRNA, the migration efficiency of hepatoma cells mediated by HBX was suppressed." (PMID 33722250, 2021). "On the one hand, PI3-K, ERK, and STAT3 signal pathways were involved in the upregulation of vimentin mediated by LASP1 in HBX-positive hepatoma cells." (PMID 33722250, 2021). "Overall, these findings indicated that the activation of PI3-K, ERK, and STAT3 pathways mediated by LASP1 was responsible for vimentin protein expression in HBX-positive hepatoma cells." (PMID 33722250, 2021). "The expression of vimentin induced by HBX, and the role of LIM and SH3 domain protein 1 (LASP1) in HBX-induced vimentin expression in hepatoma cells were examined by western blot and immunohistochemistry analysis." (PMID 33722250, 2021). "It has been reported that Survivin, Vimentin, and Snail play an important role in cell proliferation and metastasis of hepatocellular carcinoma." (PMID 32420319, 2020). "ARHGEF11-silenced hepatoma cells displayed a clear increase in E-cadherin and a decrease in Vimentin as well as ZEB1 compared with the control group." (PMID 33122451, 2020). "LncRNAs DREH and AOC4P, for instance, regulate vimentin expression during tumor metastasis or enhances vimentin degradation during hepatocellular carcinoma, respectively, leading to tumor suppressive effects." (PMID 30791369, 2019). "On the other hand, reports have shown that lower expression of miR-30a-3p is correlated with lower levels of MMP3 and vimentin as well as higher levels of E-cadherin in hepatocellular carcinoma cells." (PMID 31217934, 2019). "Characterizing hepatoma cell lines as epithelial or mesenchymal by E/N-cadherin and Vimentin expression facilities us better understanding of the cell EMT extent." (PMID 31819036, 2019). "In the present study, the expression levels of E-cadherin and vimentin in both hepatoma cell lines (PLC/PRF/5 and HepG2) were examined." (PMID 31431619, 2019). "Initially we analysed ZEB1, ZEB2, E-cadherin and vimentin expression in eight Hepatoma-derived cell lines." (PMID 31543517, 2019). "Intriguingly, tumor invasion properties and mesenchymal gene expression including increased expression of CD133, vimentin and N-cadherin and a decreased expression of E-cadherin are further enhanced in hepatoma cells in presence of both HUVECs and HBx." (PMID 31069171, 2019). "Overexpression of GAS5 downregulates the vimentin and upregulates the E-cadherin level in hepatocellular carcinoma cells." (PMID 30564069, 2018).
hepatocellular carcinoma (continued). "These were in consistent with prior research that molecular characterization of LASP1 expression revealed Vimentin as its new partner in human hepatocellular carcinoma cells." (PMID 28186968, 2017). "On the other hand, overexpression of N-cadherin and vimentin is correlated with poor prognosis in several types of cancer, including colorectal, bladder and hepatocellular carcinoma." (PMID 26934679, 2016). "Downregulation of FOXP2 also correlated with poor survival in hepatocellular carcinoma patients and enhanced cell invasiveness, reducing the expression of E-cadherin and increasing that of vimentin." (PMID 27224915, 2016). "Anti-platelet treatment induced CK8/CK18 and CK7 expression and reduced vimentin levels, indicating that clopidogrel triggered hepatoma cell differentiation." (PMID 27542264, 2016). "Studies have found that EPHA4 mediates the EMT process of human hepatocellular carcinoma by downregulating the expression of E-cadherin and vimentin." (PMID 24932309, 2014). "In this study, RYBP overexpression inhibited hepatoma cell invasion, and decreased the expression of E-cadherin and increased the expression of vimentin in vitro and in vivo." (PMID 25344099, 2014). "In contrast to in vitro observations, in vivo overexpression of TRIB3 significantly enhanced hepatoma cell proliferation and EMT, as evidenced by increased Ki67 expression in hepatoma cells and alterations in vimentin and E‐cadherin levels under long‐term sorafenib treatment." (PMID 39932456, 2025). "Similarly, Sun and colleagues reported that the mesenchymal marker Vimentin was consistently overexpressed in hepatocellular carcinomas (HCCs) compared with cirrhotic and normal liver tissues, reinforcing the association between EMT and cancer progression." (PMID 38067168, 2023). "Low-dose shikonin may inhibit the migration of hepatoma cells by downregulating the expression of vimentin and matrix metalloproteinase −2 and −9." (PMID 35293266, 2022). "Taken together, these results indicated that HBX could enhance vimentin expression to facilitate EMT in hepatoma cells." (PMID 33722250, 2021). "Besides these, vimentin was involved in the growth and migration of hepatoma cells mediated by LASP1 in HBX-positive hepatoma cells." (PMID 33722250, 2021). "Except these, LASP1 has been reported to be capable of interacting with vimentin in hepatoma cells." (PMID 33722250, 2021). "Furthermore, we found that vimentin also participates in cellular proliferation and migration mediated by LASP1 in HBX-associated hepatoma cells." (PMID 33722250, 2021). "HBX has been reported to induce the EMT phenotype in hepatoma cells, with the decreased levels of epithelial cell–cell adhesion molecule E-cadherin, while the increased expressions of cytoskeletal actin component β-catenin and vimentin." (PMID 33722250, 2021). "Besides, the effect of HBX on vimentin stability was dependent on the presence of LASP1 protein in hepatoma cells." (PMID 33722250, 2021). "The researcher showed that HBx could enhance vimentin expression to facilitate EMT in hepatoma cells." (PMID 34830378, 2021). "Furthermore, vimentin-specific shRNA was used to knock down the expression of vimentin protein in HBX-positive hepatoma cells." (PMID 33722250, 2021). "Furthermore, our results showed that PI3-K, ERK, and STAT3 pathways were responsible for vimentin expression mediated by LASP1 in HBX-positive hepatoma cells." (PMID 33722250, 2021).
hepatocellular carcinoma (continued). "Besides these, the co-location of HBX, LASP1, and vimentin was also found in hepatoma cells based on immunofluorescence assay." (PMID 33722250, 2021). "Taken together, these results indicated that HBX could promote the expression of vimentin through LASP1 in hepatoma cells." (PMID 33722250, 2021). "In addition, the expression of vimentin was examined in hepatoma cells after treatment with a proteasome inhibitor MG132." (PMID 33722250, 2021). "Moreover,its overexpression increases VIM in hepatocellular carcinoma, andsquamous cell carcinoma CSCs." (PMID 34308569, 2021). "Consequently, targeting vi-VIM on human hepatoma cells with hzVSF inhibited NTCP receptor-mediated endocytosis of HBV by likely altering the intracellular VIM localization." (PMID 34571970, 2021). "However, mesenchymal markers, including Vimentin and Fibronectin, were suppressed in the miR‐125b‐5p group hepatoma cells." (PMID 31065520, 2019). "Other than that, oleocanthal treatment on mammary cancer cells and human hepatocellular carcinoma suppressed mesenchymal marker, vimentin, and N-cadherin and stabilized ZO-1 and E-cadherin expression suggested that oleocanthal was able to modulate EMT mechanisms." (PMID 31315241, 2019). "In hepatocellular carcinoma, miR-17-3p was reported to modulate proliferation, migration, survival, morphogenesis and colony formation of HepG2 cells, and it inhibited endothelial tube formation by repressing the expression of vimentin and GalNT7." (PMID 28178677, 2017). "In patients with hepatocellular carcinoma especially vimentin and Twist expression in CTCs could serve as a biomarker for the evaluation of metastasis formation and prognosis of the disease." (PMID 27529216, 2016). "Our results indicated that transfection of C/EBPα-saRNA could suppress migration and invasion of hepatoma cells, and high expression of E-cadherin and reduction of N-cadherin, Slug, and Vimentin in C/EBPα-saRNA transfected cells." (PMID 27050434, 2016). "In this study, asialoglycoprotein receptors (ASGPR) targeting-ligand-based liposomes were tested to determine whether they can co-deliver vimentin siRNA and doxorubicin to hepatocellular carcinoma (HCC) selectively." (PMID 28335269, 2016). "Furthermore, miR-122 overexpression reduces expression of the mesenchymal proteins fibronectin and vimentin, resulting in inhibition of the migration and invasion of hepatocellular carcinoma (HCC) cells." (PMID 25839165, 2015). "Overexpression of SRF in hepatocellular carcinoma and breast cancer accelerates cell migration and invasion, and there is a subsequent acquisition of mesenchymal phenotypes due to the expression of a mesenchymal marker (vimentin)." (PMID 23426188, 2013). "MiR-127-5p overexpression in hepatocellular carcinoma cells enhances EMT progression by accelerating the activation of the SHC3/ERK signaling pathway to upregulate the expression of Vimentin and N-cadherin, suggesting that circRNAs could promote EMT by accelerating T-cell apoptosis." (PMID 40109856, 2025). "A previous paper revealed that overexpression of ARG1 led to a significant increase in the expression of Vimentin, N-cadherin, and β-catenin both at protein and mRNA levels of hepatocellular carcinoma (HCC)." (PMID 36639644, 2023). "Interestingly, we could find a trend towards increased expression of EMT markers (α-SMA and vimentin) as well as PDGFR as an angiogenesis marker in hepatocellular carcinoma from CryabTg mice." (PMID 36624493, 2023). "In addition, acetylation of vimentin is involved in hepatocellular carcinoma cell migration." (PMID 35163593, 2022). "Sarcomatoid hepatocellular carcinoma (SHC) is a rare type of HCC with positive expression of vimentin and predominantly composed of anaplastic spindle-like cells 39-41." (PMID 34149910, 2021). "We examined whether LASP1 contributes to the vimentin expression mediated by HBX in hepatoma cells." (PMID 33722250, 2021).
hepatocellular carcinoma (continued). "DREH, which plays a key role in hepatocellular carcinoma, inhibits vimentin expression by acting as a tumor suppressor and inhibits HCC growth and metastasis in vitro and in vivo." (PMID 34869051, 2021). "In the present study, we found that vimentin could mediate the expressions of E-cadherin and β-catenin in HBX-positive hepatoma cells, and facilitate the growth and migration of hepatoma cells, indicating that vimentin plays a very important role in EMT and hepatocarcinogenesis mediated by HBX." (PMID 33722250, 2021). "First, our study demonstrated that TGF-β1 made hepatoma cells became mesenchymal cells and adopted a fibroblast-like morphology, and upregulated vimentin and fibronectin, downregulated E-cadherin significantly, which indicated that TGF-β1 could induce hepatoma cells occurs EMT." (PMID 29312546, 2017). "Overexpression of CD44 is associated with low expression of E-cadherin, high expression of vimentin, a high percentage of phospho-Smad2 positive nuclei and poor prognosis in hepatocellular carcinoma (HCC) patients." (PMID 26985909, 2016). "Recent study also proved the vital role of LASP1 in tumor metastasis by working together with Vimentin in hepatocellular carcinoma (HCC) cells." (PMID 27626692, 2016). "Through the regulation of matrix metalloproteinases (MMP-2 and MMP-9) and the upregulation of E-cadherin expression, while downregulating N-cadherin and vimentin, RA also prevented the growth, invasion, and metastasis of hepatocellular carcinoma (HCC) cells in male BALB/c nude mice." (PMID 40427522, 2025). "Besides, BOP1 was reported to influence the epithelial mesenchymal transformation in hepatocellular carcinoma (HCC) through upregulating F-actin, c-catenin and vimentin, which was similar to our findings in the GC cell lines." (PMID 35222794, 2022). "In addition, HDAC6 upregulation can inhibit the mesenchymal transformation of hepatocellular carcinoma (HCC) epithelial cells by increasing the level of E-cadherin protein and reducing the levels of N-cadherin, vimentin, and MMP-9 proteins." (PMID 35449808, 2022). "SIRT1 is also upregulated in hepatocellular carcinomas (HCCs), where it increases cancer cells’ invasiveness and metastatic potential through the activation of SNAIL, TWIST, and VIMENTIN, and decreases the expression of E-cadherin." (PMID 35745656, 2022). "Furthermore, different molecular mechanisms were involved in the expression of vimentin mediated by LASP1 in HBX-positive hepatoma cells, and these findings may help us better understand the molecular mechanism of tumorigenesis mediated by HBX during HBV infection." (PMID 33722250, 2021). "We found that the expressions of vimentin and β-catenin were increased, but the expression of E-cadherin was declined in LASP1-overexpressed hepatoma cells." (PMID 33722250, 2021). "Elevated TUFT1 expression regulates CDH1 and vimentin expression through the hypoxia-inducible factor 1–SNAI1 signaling pathway in pancreatic and hepatocellular cancer metastasis." (PMID 34455105, 2021). "EMT is a well-known critical event in the progression of HCC, and we detected the expressions of EMT markers, including vimentin, E-cadherin, and β-catenin proteins in HBX-positive hepatoma cells and control cells." (PMID 33722250, 2021). "Together, these results indicate that vimentin was involved in the proliferation and migration mediated by LASP1in HBX-positive hepatoma cells." (PMID 33722250, 2021). "For HBV it has been shown that hzVSF inhibits endocytosis-based entry into human hepatoma cells via the NTCP receptor, possibly through an alteration of intracellular VIM localization." (PMID 34571970, 2021). "We found that, when the suppression of vimentin, the E-cadherin expression was increased, while β-catenin expression was reduced in HBX-positive hepatoma cells." (PMID 33722250, 2021).